E2F5 (E2F transcription factor 5)
Diseases named in the same sentence as E2F5 in open-access papers (continued):
Sharing a sentence is not in itself a finding about the gene and the disease.
CNS tumor (1 paper, 2020). "Oncomine differential expression analysis revealed that the E2F5 expression was remarkably upregulated in brain and CNS tumor in five datasets." (PMID 33381564, 2020).
prostate (1 paper, 2021). "Our findings provide the first evidence that CDK13 upregulation-induced formation of the positive feedback loop among circCDK13, miR-212-5p/miR-449a and E2F5 contributes to prostate carcinogenesis and drug resistance." (PMID 33390186, 2021). "To clarify the role of the CDK13-circCDK13-miR-212/miR-449a-E2F5 axis in prostate tumorigenesis, we established PCa xenograft models by implanting PC3 cells stably knocking down circCDK13, E2F5 or both into nude mice." (PMID 33390186, 2021).
E2F5 also shares sentences with these, for which no sentence is quoted: bladder cancer (2 papers); acute lymphoblastic leukemia (1); anaplastic astrocytoma (1); benign prostatic hyperplasia (1); cervical cancer (1); endometriosis (1); head and neck cancer (1); hemangioma (1); Infertility (1); laryngeal squamous cell carcinoma (1); lymphoma (1); metastatic cancer (1); multiple myeloma (1); non-small cell lung carcinoma (1); oral squamous cell carcinoma (1); oropharyngeal squamous cell carcinomas (1); prostate tumor (1); renal carcinoma (1); squamous cell lung carcinoma (1).